CTLA4 (cytotoxic T-lymphocyte associated protein 4)
Diseases named in the same sentence as CTLA4 in open-access papers (continued):
Sharing a sentence is not in itself a finding about the gene and the disease.
adenocarcinoma (22 papers, 2016 to 2025). A common cancer characterized by the presence of malignant glandular cells. "High epithelial CTLA-4 expression was in favour of adenocarcinoma, high-grade dysplastic adenoma and low-grade dysplastic adenoma compared to normal specimens." (PMID 35047074, 2021). "In fact, we found that patients with adenocarcinoma harboring somatic mutations of EGFR, CTLA4, PDCD1LG2, or ZEB2 that only underwent surgical treatment and developed brain metastases may have the worst prognosis." (PMID 36629526, 2023). "When evaluating only adenocarcinoma samples, only HLA-DR+ and CD8+/CTLA4+ expression remained significantly correlated with DSS." (PMID 39751903, 2025). "High CTLA-4 epithelial expression was significantly correlated with short OS (p = 0.003) and short RFS (p = 0.012) of adenocarcinoma cases." (PMID 35047074, 2021). "Monotherapy with the anti-CTLA4 agent ipilimumab showed only modest efficacy in a phase II study of both SCC and adenocarcinoma of cervix with prior exposure to platinum chemotherapy." (PMID 34640541, 2021).
infectious disease (18 papers, 2017 to 2026). A disorder directly resulting from the presence and activity of a microbial, viral, or parasitic agent in humans. "The favorable therapeutic outcomes of anti-PD-1/PD-L1 and anti-CTLA-4 in solid tumor treatment underscored the substantial research potential of this approach in infectious diseases, notably TB infection." (PMID 38957797, 2024). "Will the same targets, PD-1, CTLA-4, etc., play distinct roles in the infectious disease setting and can they be harnessed for vaccine development?" (PMID 30376867, 2018). "Yet, in infectious diseases, although preclinical and clinical research investigated various immune checkpoint targets such as the CTLA-4 and PD-1–PD-L1 axis LILRs as therapeutic targets remain to be properly appraised but represent a strong research premise in intractable infectious diseases." (PMID 34594332, 2021). "Furthermore, despite few clinical trials concerning CTLA-4 blockade to control infectious diseases, HCV patients demonstrated promising results after this therapy." (PMID 29312289, 2017). "Therefore, new discoveries concerning the role of CTLA-4 in the immune response during M. leprae infection could provide critical insight that can be applied to other infectious diseases." (PMID 29312289, 2017). "In addition, each infectious disease has its own ICP pattern of expression, as observed in HBV patients whose PD-1 expression is higher than that of CTLA-4." (PMID 29312289, 2017).
gastrointestinal tumors (10 papers, 2017 to 2025). "Furthermore, the greatest risk of all-grade PAEs in patients with digestive system tumors was linked to anti-PDL1 plus anti-CTLA4, which was significantly different from the other interventions except for anti-PD1-based interventions." (PMID 38373990, 2024). "Several vectors have been evaluated in preclinical models of gastrointestinal tumors to express ICIs against PD-1, PD-L1, and CTLA-4, among other immune checkpoints, with promising results." (PMID 37190279, 2023). "Finally, the greatest risk of grade 3–4 PAEs in patients with digestive system tumors was associated with anti-PD1 plus anti-CTLA4, which differed significantly from the other interventions except for anti-PDL1 plus anti-CTLA4, and anti-PD1 plus targeted therapy drug." (PMID 38373990, 2024). "We further found NOTCH3 levels in gastrointestinal tumor to correlate with markers of Dendritic cell(HLA-DPB1, HLA-DRA, HLA-DPA1, BDCA-4), Tfh(T-bet, STAT4, STAT1, TNF-α), Treg cells (FOXP3, CCR8, STAT5B, TGFβ) and T cell exhaustion (PD-1, CTLA4, LAG3, TIM-3)." (PMID 38906903, 2024).
genetic disorders (10 papers, 2009 to 2025). "This study provides further evidence that CTLA4 promotor polymorphisms are associated with this complex genetic disease and supports an immune mediated aetiopathogenesis of canine hypoadrenocorticism." (PMID 32835228, 2020).
inflammation (10 papers, 2014 to 2025). Aberrant reaction of the microcirculation characterized by movement of fluid and leukocytes from the blood into extravascular tissues. "CTLA-4 gMFI levels on ILC1 were also increased in the context of intestinal inflammation in IBD patients compared to healthy controls." (PMID 39496592, 2024). "Immune checkpoint inhibition can potentially lead to exacerbated allergic manifestations and animal data suggest that CTLA-4 blockade can promote allergic eosinophilic inflammation and antigen-specific IgE secretion." (PMID 30333065, 2018). "The pattern of specific endocrine toxicities varies considerably: pituitary inflammation shows predilection for CTLA-4 inhibition (occurring in ∼4% of ipilimumab-treated patients), while thyroid dysfunction predominantly accompanies PD-1 blockade and combination therapy." (PMID 40590356, 2025). "That inflammation, immune system activation and imbalance, and cell proliferation and adhesion migration were mainly affected by HLA-DRA, SYK, CTLA4, VAV1, NRAS, and JAK3 signaling pathways was suggested to be the potential molecular mechanism for pulmonary inflammation and fibrosis in ACO." (PMID 33869177, 2021).
hematologic cancer (9 papers, 2017 to 2025). "Therapies targeting the programmed death 1 (PD-1) and cytotoxic T lymphocyte-associated antigen 4 (CTLA-4), the immune checkpoints, have shown unprecedented rates of durable clinical responses in patients with several solid and hematological cancers." (PMID 40264769, 2025). "The expression of CTLA-4-specific mRNA was induced in 30% (3/10), 50% (5/10), and 20% (2/10) of CTLA-4-negative hematological cancer cells treated with guadecitabine, DAC or AZA, respectively." (PMID 30581389, 2018). "Over the past decade, immune checkpoint inhibitors targeting CTLA-4, PD-1,and PD-L1 have become standard of care across multiple solid tumors, while chimeric antigen receptor (CAR) T-cell therapies havedemonstrated remarkable efficacy in hematologic cancers." (PMID 41170078, 2025). "The most compelling data to date supporting the role of CTLA-4 in the treatment of patients with AML comes from a phase 1 multicenter study exploring the role of ipilimumab, a CTLA-4 specific ICI, in patients with recurrent hematologic cancer after allogeneic HSCT." (PMID 29951373, 2018).
bacterial infection (6 papers, 2013 to 2024). "The allele distribution of CTLA4 polymorphisms in patients with bacterial infection and non-bacterial infection." (PMID 24015180, 2013). "The genotype distribution of the CTLA4 polymorphisms in patients with bacterial infection and non-bacterial infection." (PMID 24015180, 2013). "The distribution of haplotypes in 5 locus of CTLA-4 between bacterial infection and non- bacterial infection." (PMID 24015180, 2013). "In bacterial infections, CTLA-4 has been reported to cause T cell anergy especially in H. pylori infections in mice, and pathogen clearance was improved following the blockade of CTLA-4." (PMID 28820897, 2017).
cardiac disease (6 papers, 2012 to 2022). "Cardiac disease improved in this model with a 12-week treatment with CTLA4-Ig starting at 21 days of age." (PMID 36139654, 2022). "Specific deletion of CTLA-4 in CD4+ Foxp3+ Treg cells was sufficient to induce the heart disease with cardiomegaly and mononuclear cardiac infiltration, although lifespan increased compared to full knockout animals." (PMID 36139654, 2022). "First, we evaluated adverse events on the hearts of young adult mice receiving anti-CTLA-4 antibody treatment based on both levels of cardiac troponin I (TNNI3, a routine diagnostic marker for various heart disorders) as serum marker and histological analysis." (PMID 29463898, 2018). "Conversely, a higher expression of CTLA-4 upon pan-activation of the peripheral T cell compartment was observed in patients with advanced heart disease." (PMID 22574131, 2012).
gastrointestinal disorders (5 papers, 2023 to 2025). "Among the different class-specific ICI regimens, anti-PD-1 drugs (nivolumab), anti-PD-L1 drugs (atezolizumab) and anti-CTLA-4 drugs (ipilimumab) demonstrated a significant association with gastrointestinal disorders and metabolism disorders." (PMID 39588146, 2024). "Three monotherapy (anti-PD-1, anti-PD-L1 and anti-CTLA-4) were all associated with significant increasing gastrointestinal disorders (ROR025 = 1.66, 1.16, 1.99) and metabolism disorders (ROR025 = 2.26, 1.74, 3.13)." (PMID 39588146, 2024). "The onset of skin and gastrointestinal disorders induced by anti‐CTLA‐4 monotherapy tends to be earlier than that induced by anti‐PD‐1 monotherapy, such as within the first 3–5 weeks of treatment." (PMID 37986680, 2023).
peripheral neuropathy (5 papers, 2021 to 2025). A disorder affecting the peripheral nervous system. "Applying the ROR, we found that the anti-CTLA-4 agent ipilimumab was associated with an increased reporting probability of neurologic irADRs belonging to “Peripheral neuropathies” and “Headaches” HLGTs when compared with all other ICI classes." (PMID 35372076, 2022). "Immune checkpoint inhibitors (ICIs), blocking cytotoxic T-lymphocyteassociated protein 4 (CTLA-4), programmed cell death protein 1 (PD-1), or programmed cell death ligand 1 (PD-L1), can induce an immune imbalance and cause different peripheral neuropathies (PNs)." (PMID 37006303, 2023). "Moreover, when comparing ICI classes, anti-CTLA-4 and anti-PD-1 classes were associated with a lower likelihood of reporting peripheral neuropathy compared to anti-PDL-1 (ROR 0.510; 95% CI 0.267-0.966; p=0.03; ROR 0.533; 95% CI 0.31-0.907; p=0.016, respectively)." (PMID 37006303, 2023). "Additionally, blocking CTLA‐4 may impair T‐lymphocyte and macrophage recognition of and response to antigens, resulting in endoneurial vascular inflammation and ultimately, peripheral neuropathy." (PMID 40620216, 2025).
head and neck tumours (3 papers, 2017 to 2024). "Some immune checkpoints play a role in the immune escape of head and neck tumours, including PD-1/PD-L1, CTLA-4, and indoleamine 2,3-dioxygenase 1 (IDO1)." (PMID 36405713, 2022). "Investigations have suggested that CTLA-4 and IDO1 expression levels in head and neck tumours are epigenetically regulated via DNA methylation." (PMID 36405713, 2022).
kidney disease (3 papers, 2018 to 2021). "Yu and colleagues revealed that Abatacept, a CTLA4-Ig drug, could alleviate disease progression in cases with B7-1 positive proteinuric kidney disease." (PMID 29862277, 2018). "The CTLA-4 mimicking therapeutic agents, which binds CD80, have been tested in CD80-positive proteinuric kidney disease." (PMID 32509873, 2020).
connective tissue diseases (2 papers, 2022). "Evidence on CTLA-4’s role in initiating connective tissue diseases remains to be fully elucidated, and most evidence is only on the genetic polymorphisms of CTLA-4 being associated with an increased risk of connective tissue diseases." (PMID 35784333, 2022).
hepatobiliary disorder (2 papers, 2016 to 2021). A non-neoplastic or neoplastic disorder that affects the liver, bile ducts, and gallbladder. "Ipilimumab (IPI), an anti-CTLA-4 antibody, and vemurafenib (VEM), a BRAF inhibitor, have distinct mechanisms of action and shared toxicities (e.g., skin, gastrointestinal [GI] and hepatobiliary disorders) that may preclude concomitant administration." (PMID 27532019, 2016).
retinopathy (2 papers, 2020 to 2025). "Although this interaction between Tregs and CD8+ T cells is not fully understood in retinopathy, the increased CTLA-4 in Tregs can suppress CD8+ T cells via antigen-presenting cells." (PMID 40133487, 2025).
vasculopathy (2 papers, 2017 to 2021). "Heart allografts from PI3KδD910A/D910A + multiple dose CTLA4-Ig treated mice recovered at day 100 post-transplant showed much more severe chronic rejection with lymphocyte infiltration and vasculopathy." (PMID 29038423, 2017). "However, other reports show that allografts lacking PD-L1 are still accepted in mice treated with repetitive doses of CTLA-4–Ig but exhibited severe chronic rejection and vasculopathy." (PMID 34752418, 2021).
autosomal dominant disease (1 paper, 2022). Autosomal dominant form of disease. "In the present study, we evaluated the seroprevalence of common infectious agents as a potential disease modifier factor in the context of CTLA-4 insufficiency, as this autosomal dominant disease presents with reduced penetrance." (PMID 36405723, 2022).
gastrointestinal disease (1 paper, 2018). A disease that occurs in the gastrointestinal system, excluding the hepatobiliary system. "Furthermore, this particular patient also presented with IBD-like gastrointestinal disease that was retrospectively reclassified as a CTLA4-related gastrointestinal presentation." (PMID 30723478, 2018).
movement disorder (1 paper, 2023). Neurological conditions resulting in abnormal voluntary or involuntary movement, which may impact the speed, fluency, quality and ease of movement. "The imbalance of CD28 and CTLA4 leads to high inflammatory tendency and dopamine neuron injury, which may contribute to the onset and exacerbation of movement disorders in MSA patients." (PMID 36831748, 2023).
CTLA4 also shares sentences with these, for which no sentence is quoted: multiple myeloma (15 papers); pericarditis (8); psoriatic arthritis (7); Alzheimer disease (6); glomerulonephritis (6); Infertility (5); myocardial infarction (5); undifferentiated pleomorphic sarcoma (5); viral disease (5); ANCA-associated vasculitis (4); cardiac arrhythmia (4); Evans syndrome (4); Guillain-Barre syndrome (4); immune thrombocytopenia (4); kidney failure (4); prostate (4); rheumatic diseases (4); yolk sac tumor (4); autoimmune pancreatitis (3); autoimmune polyglandular syndrome (3); cardiovascular diseases (3); Central hypothyroidism (3); chronic hepatitis C (3); chronic pancreatitis (3); digestive system cancer (3); germ cell tumor (3); intestinal disease (3); lymph node (3); metabolic disease (3); metastasis (3).
A further 258 diseases each share a sentence with CTLA4 in 3 papers or fewer.